MT-CO1 (mitochondrially encoded cytochrome c oxidase I)
Description:
Component of the cytochrome c oxidase, the last enzyme in the mitochondrial electron transport chain which drives oxidative phosphorylation. The respiratory chain contains 3 multisubunit complexes succinate dehydrogenase (complex II, CII), ubiquinol-cytochrome c oxidoreductase (cytochrome b-c1 complex, complex III, CIII) and cytochrome c oxidase (complex IV, CIV), that cooperate to transfer electrons derived from NADH and succinate to molecular oxygen, creating an electrochemical gradient over the inner membrane that drives transmembrane transport and the ATP synthase. Cytochrome c oxidase is the component of the respiratory chain that catalyzes the reduction of oxygen to water. Electrons originating from reduced cytochrome c in the intermembrane space (IMS) are transferred via the dinuclear copper A center (CU(A)) of subunit 2 and heme A of subunit 1 to the active site in subunit 1, a binuclear center (BNC) formed by heme A3 and copper B (CU(B)). The BNC reduces molecular oxygen to 2 water molecules using 4 electrons from cytochrome c in the IMS and 4 protons from the mitochondrial matrix.
Synonyms: COI; COX1; formerly MTCO1
Tractability: Small molecule: a structure with a bound ligand is known. Antibody: UniProt predicts a signal peptide or a membrane-spanning region. PROTAC: a small molecule that binds it is known.
Target class: Oxidoreduction-driven transporters; Primary active transporter; Transporter
Gene: Protein-coding gene on chromosome MT (5,904 to 7,445, forward strand). Ensembl gene ENSG00000198804.
Subcellular location: Mitochondrion inner membrane
Subcellular location (Human Protein Atlas): Mitochondria; End piece
Pathways (Reactome):
Metabolism: Complex IV assembly; Respiratory electron transport
Metabolism of proteins: Mitochondrial protein degradation; Mitochondrial translation termination
Cellular responses to stimuli: Cytoprotection by HMOX1
Gene Ontology:
Molecular function: cytochrome-c oxidase activity; protein binding; heme binding
Biological process: aerobic respiration; cellular respiration; mitochondrial electron transport, cytochrome c to oxygen; respiratory electron transport chain; cerebellum development; oxidative phosphorylation; proton transmembrane transport; response to copper ion; response to electrical stimulus; response to hypoxia; response to oxidative stress
Cellular component: mitochondrial inner membrane; mitochondrial membrane; mitochondrion; respiratory chain complex IV; membrane
Gene-disease validity (ClinGen):
ClinGen rates the evidence that MT-CO1 causes each of these diseases.
mitochondrial disease (mitochondrial): Definitive.
Leigh syndrome (mitochondrial): Limited. A progressive neurological disease defined by specific neuropathological features associating brainstem and basal ganglia lesions.
Homologues: Orthologues: chimpanzee MT-CO1 (99% identical), pig COX1 (92% identical), rabbit MT-CO1 (92% identical), guinea pig MT-CO1 (92% identical), macaque COX1 (91% identical), mouse mt-Co1 (91% identical), rat Mt-co1 (90% identical), tropical clawed frog COX1 (87% identical), zebrafish mt-co1 (85% identical), Drosophila melanogaster mt:CoI (75% identical), Caenorhabditis elegans WBGene00010964 (60% identical).
Diseases named in the same sentence as MT-CO1 in open-access papers:
MT-CO1 is named in the same sentence as 106 diseases in open-access papers, as found by Europe PMC text mining. Sharing a sentence is not in itself a finding about the gene and the disease. The quoted sentences say what the papers report.
prostate carcinoma (13 papers, 2012 to 2025). A carcinoma that arises from epithelial cells of the prostate gland. "Mutations within MT‐CO1 have also been described as important contributors in the aetiology of prostate cancer." (PMID 35842901, 2022). "For example, MT-ND5 is mutated in many types of cancer, NADH: ubiquinone oxidoreductase core subunit 4 (MT-ND4) is frequently mutated in lung and prostate cancer, and Cytochrome c oxidase I (MT-CO1) is mutated in breast tumors." (PMID 34298989, 2021). "Mutations in MTCO1 are associated with a higher risk of developing prostate cancer, although these mutations were initially detected in colon cancer cells." (PMID 26462158, 2015). "The second variant m.6253T > C (p.M117T, MTCO1) has been reported with an association to prostate cancer and the third variant m.7444G > A (p.*514K, MTCO1) in association with Leber’s hereditary optic neuropathy or deafness." (PMID 23870133, 2013). "Recent studies have demonstrated that detrimental alterations in mitochondrial complex I and IV genes, including MT-ND4 and MT-CO1, are linked to enhanced oxidative phosphorylation activity and increased aggressiveness in high-grade and treatment-resistant prostate cancers." (PMID 40491606, 2025). "Missense mutations in MTCO1 have been detected in 11-12% of all prostate cancer patients." (PMID 26462158, 2015). "Further data demonstrate that both germ-line and somatic mtDNA mutations contribute to prostate cancer, and about 11% of all prostate cancer patients harbored mt-CO1 (mitochondrially encoded cytochrome c oxidase I) mutations." (PMID 31027297, 2019). "Within 260 prostate cancer samples, 12% of patients were found to harbour MT‐CO1 missense mutations, while only 1.9% of 54 prostate cancer‐negative controls demonstrated mutations of this type." (PMID 35842901, 2022).
ovarian carcinoma (7 papers, 2008 to 2025). A malignant neoplasm originating from the surface ovarian epithelium. "A mtDNA cytochrome c oxidase subunit 1 (MT-CO1) variant has been associated with protection for ovarian cancer, as we also observed." (PMID 39941116, 2025). "The variant C7028T in the MT-CO1 gene was reported in ovarian cancer patients and Parkinson disease." (PMID 22312186, 2012). "A variant, C7028T in the MT-CO1 gene, had an ascending frequency from borderline (8%) to stages III/IV (75%) among the three ovarian cancer subtypes and stages." (PMID 18662401, 2008). "An increased risk of ovarian cancer has been associated with mutations in the MT‐CO1 gene, while the recent Pan‐Cancer Analysis of Whole Genomes (PCAWG) Consortium report MT‐CO1 as the most frequently mutated mtDNA protein‐encoding gene in breast, cervical and bladder cancers." (PMID 35842901, 2022). "Furthermore, it was found that inhibiting LRPPRC expression not only diminishes the translation of the core subunit MTCO1 of complex IV and the copper chaperone molecule SCO1 in A2780 and SKOV3 ovarian cancer cells, but also reduces the expression levels of FDX1 and LIAS." (PMID 41516324, 2025).
Parkinson disease (6 papers, 2012 to 2026). A progressive degenerative disorder of the central nervous system characterized by loss of dopamine producing neurons in the substantia nigra and the presence of Lewy bodies in the substantia nigra and locus coeruleus. "Similarly, decreased expression of mitochondrial genes such as MT‐CO1, MT‐CYB, and MT‐ATP6 in dopaminergic subclusters points to impaired oxidative phosphorylation, which could contribute to parkinsonism, ataxia, and other movement disorders arising from energy failure in motor circuitry." (PMID 41355579, 2026). "In amygdala, the overall piRNAs-aligned pseudogenes ratio is not different in Parkinson’s disease, but some related pseudogene-aligned piRNAs, including HSP90, MTCO1, MTCO2, YWHAZ, GAPDH, and MTND were upregulated in the PD group." (PMID 35269612, 2022).
Sepsis (6 papers, 2012 to 2024). Sepsis is defined as life-threatening organ dysfunction caused by a dysregulated host response to infection. "Remarkably, in our study, mitochondrial function-related indicators, including mt-CO1, mt-ND1, and mt-ATP6, exhibited significantly higher discriminative capabilities for predicting the clinical outcomes of sepsis-associated lethality compared to traditional laboratory indicators." (PMID 39113822, 2024). "Furthermore, we identified that the expression of mt-ND1, mt-CO1, and mt-ATP6 was associated with sepsis-related death, which had been confirmed by AUC under ROC calculations." (PMID 39113822, 2024). "Univariate analysis revealed a significant reduction in the expression of mt-CO1, mt-ND1, and mt-ATP6 in patients with sepsis." (PMID 39113822, 2024). "In comparison to other laboratory parameters, the expression levels of mt-CO1, mt-ND1, and mt-ATP6 demonstrate notable potential in predicting the prognosis of pediatric sepsis." (PMID 39113822, 2024). "Notably, when compared to other laboratory parameters, the expression levels of mt-CO1, mt-ND1, and mt-ATP6 demonstrate promising potential for assessing the prognosis of pediatric sepsis." (PMID 39113822, 2024).
adenoma (4 papers, 2006 to 2021). A neoplasm arising from the epithelium. "It revealed that genes MT-CO1, MT-ND5 and three tRNAs (asparagine, cysteine and lysine) were reduced in adenomas." (PMID 30619609, 2018).
brain tumors (4 papers, 2022 to 2025). "Interestingly, CASP3 and CYP1A1 were previously identified to be related to glioma and used to predict the survival for glioma patients, the high expression of CDK1 is associated with the malignant progression in glioma, and mutations in MT-CO1 contribute to brain tumours." (PMID 38642129, 2024). "Three MT-CYB polymorphisms: A14793G, A15758G and A15218G, as well as the MT-CO1 G7444A, MT-CYB T15663C and G8959A (ATP6) mutations, may affect the function of mitochondria, thus potentially playing an important role in the formation of brain tumours." (PMID 36292984, 2022).
COVID-19 (4 papers, 2022 to 2024). A disease caused by infection with severe acute respiratory syndrome coronavirus 2. "Thus, the higher risk of cardiovascular disease in patients with COVID-19 is partially explained by the differential expression of the MT-CO1 gene in vascular endothelial cells." (PMID 37109540, 2023). "Using this approach, genes S100A8, IFI27, CLU, IFITM3, and MT-CO1 have been identified as the stable gene panel for the classification of severe COVID-19 patients, utilizing the same training dataset as previously employed." (PMID 39350339, 2024). "In 2022, researchers found low mRNA levels of MT-CO1 in patients with COVID-19, and another article noted that MT-CO1 was downregulated in patients with COVID-19 and recovered individuals." (PMID 37109540, 2023). "In 2022, researchers found reduced mRNA levels of MT-CO1 in patients with COVID-19, validating this parameter." (PMID 37109540, 2023). "The differential expression of MT-CO1 in vascular endothelial cells due to COVID-19 may contribute to a range of cardiovascular diseases." (PMID 37109540, 2023). "On the other hand, 450 (22.96%) and 63 (41.18%) DEGs were downregulated (Down) in COVID-19 patients and recovered subjects, respectively, and of them, only 12 genes (i.e., MAFF, ARHGEF12, DCUN1D3, DR1, MT-CO1)." (PMID 36059456, 2022).
asthma (3 papers, 2020 to 2025). "Only 3 (PTCD1, CYC1 and MT-CO1) of the 48 significantly differentially expressed genes were more highly expressed in individuals with asthma; the other 45 had lower expression in individuals with asthma as compared with individuals without asthma." (PMID 33237978, 2020).
gastric cancer (3 papers, 2021 to 2025). A primary or metastatic malignant neoplasm involving the stomach. "The aim of this study was to evaluate the expression of MCT1, MCT4, and MTCO1 and their association with clinicopathological parameters and prognostic significance in a cohort of gastric cancer patients." (PMID 33946786, 2021). "In this study, we evaluated the expression of MCT1, MCT4, and Mitochondrial cytochrome c oxidase (MTCO1) and their association with clinicopathological parameters and prognostic significance in a cohort of 568 surgically treated gastric cancer patients." (PMID 33946786, 2021). "As a next step, immunocytochemical evaluation was performed of cytochrome c oxidase subunit I (MTCO-1) and 8-hydroxy-2’-deoxyguanosine (8-OHdG) in the resistant and sensitive gastric cancer cells after normal and simulated microgravity with doxorubicin." (PMID 35629774, 2022). "The present study aimed to evaluate associations between cytoplasmic MCT1, MCT4, and mitochondrial cytochrome c oxidase (MTCO1) expression and clinicopathological variables or survival in gastric cancer." (PMID 33946786, 2021). "The results suggest that monocarboxylate transporters and MTCO1 are associated with gastric cancer progression but have no independent prognostic relevance." (PMID 33946786, 2021).
glioma (2 papers, 2018 to 2024). A benign or malignant brain and spinal cord tumor that arises from glial cells (astrocytes, oligodendrocytes, ependymal cells). "MT-CO1 protein content was decreased with doxycycline concentrations of 1 μg/mL and higher in all three glioma cell lines." (PMID 29772845, 2018).
pancreatic cancers (2 papers, 2021 to 2023). "Major mitochondrial genes including MT-ND3, MT-CO1, IDH2, and TFAM are being reported in various pancreatic cancers, including PDAC (based on cBioportal data), but their actual roles in PDAC progression need further validation." (PMID 36831413, 2023).
virus infection (2 papers, 2019 to 2023). "The virus infection significantly increased the expression of subunit SDHB (succinate dehydrogenase) and MTCO1 (cytochrome c oxidase subunit I), critical components of RC complexes II and IV, respectively." (PMID 31011285, 2019). "However, the increased expression of TFAM corroborated well with our findings that virus infection enhanced the expression of SDHB and MTCO1, components in mitochondrial RC complexes." (PMID 31011285, 2019).
Alzheimer disease (1 paper, 2023). A progressive, neurodegenerative disease characterized by loss of function and death of nerve cells in several areas of the brain leading to loss of cognitive function such as memory and language. "The increased expression of MT-CO1 (mitochondrial COX1) has been reported in blood samples from Alzheimer’s disease." (PMID 38002279, 2023).
atherosclerosis (1 paper, 2023). A disease characterized by the build-up of fatty material and calcium deposition in the arterial wall resulting in partial or complete occlusion of the arterial lumen. "In addition, MT-CO1 downregulation produces mitochondrial oxidative stress, which may increase the risk of atherosclerosis and coronary artery disease." (PMID 37109540, 2023).
Barrett esophagus (1 paper, 2017). Esophageal lesion lined with columnar metaplastic epithelium which is flat or villiform. "In conclusion, the expression of MCT1, MCT4 and MTCO1 increase from Barrett's esophagus to dysplasia indicating metabolic alteration during dysplastic progression." (PMID 28206968, 2017).
coronary artery disease (1 paper, 2023). "Reduced MT-CO1 expression in this rule may increase the incidence of coronary artery disease and contributes to poor outcomes in patients with coronary artery disease." (PMID 37109540, 2023).
craniopharyngioma (1 paper, 2021). A benign, partly cystic, epithelial tumor of the sellar region, presumably derived from Rathke pouch epithelium. "Craniopharyngioma (n = 24) similarly showed a paucity of mtDNA alterations with just 5 heteroplasmic mutations identified, one of which was a missense mutation in MT-CO1." (PMID 34337412, 2021).
dilated cardiomyopathies (1 paper, 2024). "Alterations in mtDNA genes such as NADH-dehydrogenase genes (MT-ND1, MT-ND5 and MT-ND6), cytochrome b (MT-CYB), cytochrome c oxidase I and II (MT-CO1 and MT-CO2), and ATP synthase 6 (MT-ATP6), have been described in dilated cardiomyopathies." (PMID 38391966, 2024).
dysplasia (1 paper, 2017). A usually neoplastic transformation of the cell, associated with altered architectural tissue patterns. "Cytoplasmic MCT1, MCT4 and MTCO1 expression linearly increased from normal epithelium to Barrett's mucosa to dysplasia and cancer." (PMID 28206968, 2017). "The aim of this study was to assess the metabolic changes during development of esophageal adenocarcinoma by evaluating MCT1, MCT4 and mitochondrial cytochrome c oxidase (MTCO1) in different stages of esophageal metaplasia-dysplasia-adenocarcinoma-sequence." (PMID 28206968, 2017). "Epithelial cytoplasmic MCT- and MTCO1 expression linearly increased towards dysplasia and adenocarcinoma." (PMID 28206968, 2017). "In this study we characterized MCT1, MCT4 and MTCO1 expression in esophageal metaplasia–dysplasia–adenocarcinoma sequence." (PMID 28206968, 2017).
epilepsy (1 paper, 2013). A brain disorder characterized by episodes of abnormally increased neuronal discharge resulting in transient episodes of sensory or motor neurological dysfunction, or psychic dysfunction. "The five nonsynonymous mutations with previous disease association were not predicted to be deleterious but, interestingly, m.6489C > A (p.L196I, MTCO1) has been reported to be associated with therapy-resistant epilepsy." (PMID 23870133, 2013).
esophageal adenocarcinoma (1 paper, 2017). A malignant tumor with glandular differentiation arising predominantly from Barrett mucosa in the lower third of the esophagus. "We showed that expression increased during esophageal adenocarcinoma carcinogenesis with the highest MTCO1 expression in adenocarcinoma indicating increased activity of aerobic mitochondrial energy metabolism." (PMID 28206968, 2017).
esophageal squamous cell carcinoma (1 paper, 2021). Esophageal squamous cell carcinoma (ESCC) is a type of esophageal carcinoma (EC) that can affect any part of the esophagus, but is usually located in the upper or middle third. "A Japanese study reported that the downregulation of MTCO1 induced radioresistance in esophageal squamous cell carcinoma." (PMID 33946786, 2021).
gastric adenocarcinoma (1 paper, 2021). "The high expression of MCT1 and MCT4 and low expression of MTCO1 in tumor cells may be associated with poor prognostic variables, but they seem to have no independent prognostic significance in surgically treated gastric adenocarcinoma." (PMID 33946786, 2021). "In this study, we characterized MCT1, MCT4, and MTCO1 expressions in gastric adenocarcinoma." (PMID 33946786, 2021).
kidney cancer (1 paper, 2019). Primary or metastatic malignant neoplasm involving the kidney. "(B) H-scores of immunohistochemical (IHC) staining for the mtDNA-encoded MT-CO1 protein across different subtypes of kidney cancers (pRCC, papillary RCC; chRCC, chromophobe RCC) **, p<0.01, ***, p<0.001, ****, p<0.0001, t-test." (PMID 30924768, 2019).
lung carcinoma (1 paper, 2024). "Expression levels of MTCO1, UQCRC2, and COXIV were higher in BrM lesions as compared with primary lung cancers." (PMID 39593114, 2024). "Moreover, we performed the IHC staining of 49 pairs of primary lung cancers and BrM lesions from both SYSUCC and WCH cohorts in order to independently validate the expression of MTCO1, UQCRC2, and COXIV at the protein level." (PMID 39593114, 2024).
mild cognitive impairment (1 paper, 2023). "The mitochondrial coding and non-coding RNA are increased in the circulating extracellular vesicles in AD and mild cognitive impairment (MCI); the AD genes in the category of this study include MT-ND1-4,6, MT-ND4L, MT-ATP6, MT-ATP8, MT-CYB (or MT-CYBT), MT-CO1, and MT-RNR1." (PMID 36982253, 2023).
Obesity (1 paper, 2024). Accumulation of substantial excess body fat. "The oxidative phosphorylation (OXPHOS) system, crucial for cell energy and survival, is influenced by the mitochondrial encoded cytochrome c oxidase I, II (MT-CO1 and MT-CO2) genes, previously linked to obesity." (PMID 39464187, 2024).
primary ovarian insufficiency (1 paper, 2015). "In summary, we found a high incidence of MT-CO1 missense mutations in patients with idiopathic primary ovarian insufficiency and identified two novel missense mutations in the mitochondrial cytochrome c oxidase 1 gene that were predicted to be damaging." (PMID 26225554, 2015). "Our results show that patients with primary ovarian insufficiency exhibit an increased incidence of mitochondrial cytochrome c oxidase 1 gene mutations, suggesting that MT-CO1 gene mutation may be causal in POI." (PMID 26225554, 2015).